CRP (C-reactive protein)
Diseases named in the same sentence as CRP in open-access papers (continued):
Sharing a sentence is not in itself a finding about the gene and the disease.
diabetes (continued). "Besides the vascular access types, the overall mortality rates were significantly higher among elder, high high-sensitivity CRP (hsCRP), diabetes mellitus, lower albumin, and high AST/ALT patients." (PMID 31341241, 2019). "With this AUC, RBP4 presented a greater discriminatory ability to diagnose DR compared with HbA1c (AUC 0.71; 95% CI: 0.63–0.78; P<0.001), Hs-CRP (AUC 0.65; 95% CI: 0.59–0.72; P<0.001), diabetes duration (AUC 0.62; 95% CI: 0.55–0.69; P<0.001), and HOMA-IR (AUC 0.73; 95% CI: 0.68–0.80; P=0.005)." (PMID 30135138, 2018). "The reason why retinal vascular caliber is increased in diabetes is not known, but increased C-reactive protein is associated with wider venular diameter in several populations." (PMID 29335432, 2018). "Diabetes accompanied by inflammation and heart disorder is correlated with increased inflammatory biomarkers and cytokines, and therefore, plasma E-selectin, CRP, and IL-6 can be augmented in diabetic rats." (PMID 30510626, 2018). "Elevated RDW levels were significantly associated with sarcopenia after adjusting for age, sex, race, education, household income, smoking, physical activity, hypertension, diabetes, cardiovascular disease, C-reactive protein, and hemoglobin (OR of highest quartile: 1.72 (95% CI: 1.43, 2.06))." (PMID 30065297, 2018). "With this AUC, RBP4 presented a greater discriminatory ability to diagnose VTDR compared with HbA1c (AUC 0.76; 95% CI: 0.70–0.82; P<0.001), Hs-CRP (AUC 0.71; 95% CI: 0.65–0.78; P<0.001), diabetes duration (AUC 0.77; 95% CI: 0.71–0.83; P<0.001), and HOMA-IR (AUC 0.80; 95% CI: 0.74–0.86; P<0.001)." (PMID 30135138, 2018). "Noteworthy, the association found in high hs-CRP was independent of age, gender, smoking, hypertension, and diabetes." (PMID 30147446, 2018). "Furthermore, the combined model II (RBP4/HOMA-IR/diabetes duration/Hs-CRP/HbA1c) improved the ability of every single marker and model I to diagnose DR (AUC of the combined model 0.87; 95% CI: 0.80–0.92; P<0.05)." (PMID 30135138, 2018). "This, to some degree, may explain the persisted association between the HW phenotype and CKD, even after adjusted for gender, age, BMI, CRP, serum uric acid, diabetes, hypertension, and other potential confounders." (PMID 29372543, 2018). "Individuals whose SMI increases were > 1% over a year had AHRs of 0.71 (95% CI 0.59–0.84, P < 0.001), for developing metabolic syndrome compared with individuals whose SMI changes were < 0% after adjusting for age, sex, BMI, family history of diabetes, smoking, exercise, and CRP levels, (Model 4)." (PMID 29402279, 2018). "Medications that were commonly taken for hypertension (angiotensin-converting enzyme inhibitors/angiotensin receptor blockers), high cholesterol (statins), diabetes, inflammation (cyclooxygenase inhibitors), and antiplatelet agents (clopidogrel, abciximab) have also been found to lower CRP levels." (PMID 30613458, 2018). "Since CRP in the diabetes patients was significantly higher than in the control, the results of CRP, triglycerides and HOMAIR may therefore be predictive of an increased cardiovascular risk independent of the lipid profile." (PMID 29975702, 2018). "Data from current study showed that arginase-1 and variants of ARG1 may be associated with increased risk of promoting an inflammatory response as evidenced by elevated CRP levels in type 2 diabetes mellitus." (PMID 30233283, 2018). "When compared with the remaining participants, subjects who died during follow-up were older, more frequently men, had a higher prevalence of smoking habit and previous coronary artery disease but a similar rate of diabetes, eGFR and equivalent BMI, lipid profile, high-sensitivity CRP and TNF-α." (PMID 30271669, 2018). "‡Additionally adjusted for diabetes, systolic blood pressure, antihypertensive medications, smoking status, body mass index, low-density lipoprotein cholesterol, high-density lipoprotein cholesterol, statin use, and C-reactive protein." (PMID 28332475, 2017).
diabetes (continued). "Diabetes mellitus (OR = 16; 95% CI [1.7–153.5]; p = 0.016), increased blood urea nitrogen (OR = 1.12; 95% CI [1.02–1.20], p = 0.016), and decreased C-reactive protein (OR = 0.97; 95% CI [0.96–0.99]; p = 0.027) were identified as independent factors predicting increased pancreatic enzymes." (PMID 28725436, 2017). "However, the mean age and CRP levels, frequencies of diabetes, prior congestive heart failure, and acute coronary syndrome on CA were significantly higher in the patients who died than in those who survived." (PMID 28798540, 2017). "In MetS subjects, the L/A ratio remained positively related with TSH after adjustment for age, sex, diabetes status, hs-CRP and the use of antihypertensive and glucose lowering medication (β = 0.283, P = 0.018), as well as after adjustment for individual MetS components (β = 0.294, P = 0.020)." (PMID 28077136, 2017). "Although the meta-analysis revealed a statistically significant increased diabetes risk associated with CRP, the results are not entirely consistent and a number of studies did not report any significant association either in the whole population or in men." (PMID 28178951, 2017). "However the mean of hs-CRP of the patients with well-controlled diabetes based on HbA1c levels was significantly less than that of the patients with non-controlled diabetes." (PMID 28886725, 2017). "Stratified analyses revealed that elevated serum hs-CRP level was proportionally and intensely associated with an increased prevalence of diabetes among subjects without a family history of diabetes." (PMID 28361994, 2017). "In this large prospective population-based cohort study, we found that serum level of DHEA was inversely associated with risk of type 2 diabetes, independent of established diabetes risk factors including BMI, fasting glucose, insulin and CRP." (PMID 27771738, 2017). "For individuals with diabetes, age and hs-CRP (whether on a continuous scale or stratified) were independent predictors." (PMID 28713837, 2017). "Consistent CRP elevation positively correlates with the development of diabetes later in life." (PMID 29177105, 2017). "CRP could be the intermediate factor between these indicators and chronic diseases such as hypertension, diabetes mellitus, and cardiovascular diseases as well as obesity." (PMID 28115972, 2017). "It was observed impact of C-reactive protein in the development of type 2 diabetes mellitus." (PMID 28403353, 2017). "Both studies have also adjusted for HbA1c in the statistical models, and the positive association between CRP and incident diabetes did not change materially." (PMID 28178951, 2017). "After adjusting for confounders, including age, diabetes, creatinine clearance, female gender, weight>60kg, smoke, C-reactive protein (CRP) >3mmol/l and LVEF, significant Δcystatin C (≥0.3 mg/dL or ≥10%) was not an independent risk factor for long-term mortality (HR=1.08, 95%CI, 0.34-3.43, P=0.902)." (PMID 29312646, 2017). "One study showed that obesity is associated with increased salivary level of CRP, while another study showed that IL-1β concentration in saliva is associated with periodontal disease severity rather than diabetes." (PMID 28253297, 2017). "Correlation studies on obesity and type II diabetes also showed that significantly high level of CRP was seen in obese people both in diabetes group and control group, suggesting that CRP might be the major link between obesity and type II diabetes." (PMID 28115972, 2017). "CRP is an important marker of systemic inflammation, which has been physiologically related to atherosclerosis, pre-diabetes, is observed at high concentrations in neuropathic individuals and correlates with increased macular thickness in patients with diabetic retinopathy." (PMID 29075332, 2017). "Therefore, we believe the presence of comorbid diseases, such as diabetes, hypertension and dyslipidemia, elevate CRP and IL-6 levels and contribute to sarcopenia." (PMID 28851881, 2017).
diabetes (continued). "Besides smoking, other confounders such as diabetes mellitus, hypertension and CRP were further analyzed." (PMID 28814274, 2017). "The connection between WNT5A expression in VAT and IL-6/CRP levels is of particular relevance, given the large body of clinical evidence that links increased IL-6 signaling and/or increased circulating CRP levels to insulin resistance, diabetes and atherosclerotic CVD4,40–43." (PMID 29229927, 2017). "Significant associations between GDF15 levels and CRP levels have previously been reported in patients with non-ST elevation acute coronary syndrome, diabetes, morbid obesity, and cancer." (PMID 28798540, 2017). "Although we included a wide range of inflammatory markers in the adjustment there may exist other important inflammatory markers, such as interleukin-6 (IL-6) and C-reactive Protein (CRP), that may be associated with poor lung function and diabetes." (PMID 27165091, 2016). "We hypothesize that inflammation-related epigenetic features may explain at least part of the observed associations between CRP, a sensitive marker of chronic low-grade inflammation, and related clinical events including CHD and diabetes." (PMID 27955697, 2016). "Moreover, in patients suffering from both diabetes and PAD, there was a correlation between the concentration of IL-6 and the concentrations of CRP and fibrinogen, which was consistent with the results we obtained for patients suffering from diabetes." (PMID 27834825, 2016). "A PubMed search was conducted for “high-sensitivity C-reactive protein” (hs-CRP) in combination with the terms race, ethnicity, gender, prevalence, geographic, epidemiology, cardiovascular, obesity, diabetes, hypertension, cholesterol, smoking, ischemic heart disease, stroke, and mortality." (PMID 27166776, 2016). "Diabetes and CRP over 150 mg/l were however not of significant value in this analysis, which might speak for a correlation between diabetes and the development of gangrene and an abscess leading to high CRP levels." (PMID 27891173, 2016). "The host immune response to H. pylori infection is complex and involves up regulation of several pro-inflammatory cytokines, such as C-reactive protein (CRP), interleukin 6 (IL-6), and tumor necrosis factor- α (TNF-α), which are implicated in insulin resistance and the development of diabetes." (PMID 27148410, 2016). "In the uremic milieu, the level and composition of human L5 are altered and are associated with endothelial dysfunction and increased risk of CAD, independent of diabetes, calcium–phosphate product, and Hs-CRP." (PMID 26765403, 2016). "Participants in the highest quartile of ferritin were more likely to be in a middle-aged or older age group, to have a BMI≥30kg/m2, and to have hypertension, diabetes, and a higher pulse pressure and higher c-reactive protein levels compared to the lowest quartile." (PMID 27973582, 2016). "Gangrene and an abscess might however be hard to recognize prior to the operation and therefore CRP levels and history of diabetes might be of better use when estimating the difficulty of the planned procedure." (PMID 27891173, 2016). "In line with this, the analysis of the clinical and biochemical parameters at baseline and at 12 months after LRYGB of 30 out of our 75 patients without second liver biopsy also showed a significant improvement of fasting insulin, glycaemia, HOMA-IR, metabolic syndrome, diabetes, and CRP." (PMID 27594839, 2016). "In the Cardiovascular Health Study (CHS), only C-reactive protein (CRP) and not leukocyte count was associated with the development of diabetes." (PMID 26891449, 2016). "Multivariable Cox proportional hazards modeling was performed to examine the association between leptin levels with incident cancer after adjusting for age, sex, race, smoking status, alcohol use, family history of malignancy, body mass index (BMI), diabetes mellitus and C-reactive protein." (PMID 27636369, 2016).
diabetes (continued). "In the multivariate analysis, presence of history of diabetes mellitus, hypertension or dyslipidemia for 10 or more years, smoking, elevated CRP (>3 mg/dl), hyperhomocysteinemia (>15 mg/dl) were found to be independent risk factors for PAD among Sri Lankan adults." (PMID 27938397, 2016). "However, in this study OSAS patients had higher BMI versus non-OSAS subjects and the control group included patients with comorbidities such as arterial hypertension, diabetes, and cardiovascular disease, all conditions influencing CRP levels." (PMID 27843647, 2016). "Predictive factors of death directly attributable to SA were older age, high serum CRP levels, RA and other inflammatory disease, diabetes mellitus, and confusion on admission, bacteriema, skin involvement (leg ulcers and/or eschars) and a low creatinine clearance rate." (PMID 27246346, 2016). "One variable of interest is C-reactive protein (CRP) in adults—mainly, whether the distribution of CRP differs with diabetes diagnosis." (PMID 27034909, 2016). "N-3 PUFAs decrease CRP concentration in type-2 diabetes mellitus." (PMID 27544079, 2016). "Results of selected simulation studies are presented in Section 4 followed by an illustrative example in Section 5 in which we explore the motivating example (differences in CRP distribution among diabetes groups) by testing several hypotheses." (PMID 27034909, 2016). "Epidemiologists found that elevated CRP levels could be examined in patients with acute viral hepatitis, cardiovascular disease and type 2 diabetes mellitus." (PMID 25874450, 2015). "Copeptin was strongly associated with heart rate (a marker of increased sympathetic nervous system) and was also strongly correlated with CRP (inflammation) and vWF (a marker of endothelial dysfunction), factors shown to be related to insulin resistance and diabetes." (PMID 26158609, 2015). "CRP levels were measured at baseline and 1 year after randomisation to atorvastatin in 2,322 patients with type 2 diabetes (40–75 years, 69% males) in a secondary analysis of the Collaborative Atorvastatin Diabetes Study, a randomised placebo-controlled trial." (PMID 25899452, 2015). "C-reactive protein (CRP) is a protein of acute phase condition and a strong biomarker of inflammation in the progression of various diseases like coronary heart disease, cancer, diabetes, and others." (PMID 26273663, 2015). "The higher diabetes risk associated with elevated copeptin remained after adjustment for WC, lifestyle characteristics, social class, renal function (eGFR), use of antihypertensive treatment, statin use, systolic BP, GGT, triglycerides, CRP, and vWF." (PMID 26158609, 2015). "Circulating markers of inflammation include C-reactive protein (CRP), interleukin-6 (IL-6), fibrinogen, and tumor necrosis factor-alpha (TNF-α), some of which have been associated with cognitive dysfunction in people with diabetes." (PMID 26060511, 2015). "Individuals who develop diabetes typically have higher CRP levels." (PMID 26596471, 2015). "CRP was significantly elevated in the diabetes group both at baseline and at follow-up." (PMID 26408307, 2015). "The clinical characteristics of the PAD patients that underwent femoralis TEA were as follows: median age 73 years; 75% males; 92% arterial hypertension; 33% diabetes mellitus; 33% hyperlipidemia; 17% smoking; median leukocytes 13.8 gpt/L, median CRP 47,2 mg/dL, and median creatinine 68 mmol/L." (PMID 25960616, 2015). "The present clinical trial study was designed to assess the effect of topical application of melatonin on serum levels of tumor necrosis factor-alpha (TNF-α), interleukin-6 (IL-6) and C-reactive protein (CRP) in patients with diabetes and periodontal disease in comparison with healthy controls." (PMID 26644840, 2015). "Although elevated CRP was associated with higher blood glucose (new diabetes) in the 25–59 year age group, this was not the case in the older group (data not shown)." (PMID 26167206, 2015).
diabetes (continued). "Of interest is that elevated C-reactive-protein (CRP), as well as high prevalence of cardiovascular disorders, type 2 diabetes mellitus, hypertension and obesity, are observed in early onset BD and that some of these conditions even precede the diagnosis of BD in pediatric patients." (PMID 25790282, 2015). "The cross-sectional positive association between CRP and HbA1c levels has been previously shown in studies involving participants with diabetes and without diabetes among different populations and age groups." (PMID 25994228, 2015). "C-reactive protein (CRP), tumor necrosis factor- (TNF-α) and interleukin-6 (IL-6) are mediators widely described in worldwide literature have been associated with depression, MCI and diabetes." (PMID 25793613, 2015). "Hence, a cross-sectional study was conducted to determine the effect of topical melatonin application on serum TNF-α, IL-6 and CRP concentrations in patients with diabetes and periodontal disease and in a control group of healthy subjects." (PMID 26644840, 2015). "CRP levels may fluctuate with various factors such as high blood pressure, alcohol use, smoking, chronic fatigue, diabetes, sleep disturbances, depression, many other systemic diseases, and pregnancy or lactation." (PMID 26346216, 2015). "Other data from the same study demonstrated that higher baseline C-reactive protein (CRP) was significantly associated with subsequent development of non-AIDS-defining clinical events (diabetes, cardiovascular disease, cancer, pneumonia)." (PMID 26287742, 2015). "Similarly, in diabetic patients participating in the present study, diabetes mellitus was accompanied by obesity and CRP levels were slightly raised as compared with metabolically healthy individuals." (PMID 26074960, 2015). "In addition, male sex, diabetes duration, HbA1c, Hs-CRP and systolic BP were also can be seen as DR predictors in multivariate analysis." (PMID 26136138, 2015). "The major clinical risk factors for AF are advancing age, male gender, hypertension, diabetes, obesity, heart failure, valve disease, MI, smoking, and alcohol consumption, but biomarkers such as B-type natriuretic peptide and C-reactive protein also correlate with AF." (PMID 26324443, 2015). "When comparing premenopausal and postmenopausal groups, parameters such as age, BMI, prevalence of hypertension, diabetes mellitus and dyslipidemia and blood concentrations of uric acid, C-reactive protein and homocysteine were found to be significantly different." (PMID 25627797, 2015). "Adipokine and CRP levels are significantly associated with insulin resistance and microvascular and endothelial dysfunction in young adults without diabetes or hypertension." (PMID 26549941, 2015). "While a number of studies have shown a strong association between CRP and CVD, there is evidence that the relationship may lessen in relation to diabetes status." (PMID 25788869, 2015). "Other significant variables include age (HR 1.072, P 0.0003), diabetes mellitus (HR 4.011, P 0.002), eGFR (HR 0.966, P 0.01), systolic blood pressure (HR 1.025, P 0.02), hemoglobin (HR 0.743, P 0.02), C-reactive protein (Ln) (HR 1.532, P 0.02) and PTH (Ln) (HR 1.680, P 0.01)." (PMID 24912660, 2014). "The key contributing factors to vasculopathy in diabetes are oxidative stress, inflammation and cell adhesion, also the inflammatory protein C-reactive protein (CRP), and soluble intracellular adhesion molecule sICAM-1 and sE-selectin as indicators of endothelial activation." (PMID 25287126, 2014). "GFR, diabetes mellitus, hypertension and CRP are full adjustment factors, which may influence the effect of ALP on CHD and CVD events." (PMID 25033287, 2014). "The data obtained in the present study showed that older patients with diabetes consuming diets with low level of Ca had higher CRP level, which may contribute to high CVD risks." (PMID 25078288, 2014).